ACE (angiotensin I converting enzyme)
Diseases named in the same sentence as ACE in open-access papers (continued):
Sharing a sentence is not in itself a finding about the gene and the disease.
Hypertension (continued). "Recognized as a potential target for hypertension treatment, the angiotensin-converting enzyme (ACE) is the key enzyme for blood pressure regulation and is mainly localized on the membranes of lungs, heart, kidney, and intestinal cells." (PMID 37049880, 2023). "In our subanalysis, we found that the percentage of PPCM patients with hypertension (44.4% vs. 8%, p = 0.032) and a history of preeclampsia (77.8% vs. 32%, p = 0.025) was higher in the ACE DD genotype group than in the other genotype groups." (PMID 37089887, 2023). "Phenolic chemicals have been used to treat hypertension by inhibiting the angiotensin-converting enzyme (ACE)." (PMID 37367648, 2023). "Angiotensin–converting enzyme (ACE) inhibitors are the primarily chosen drugs to treat various cardiovascular diseases, such as hypertension." (PMID 38137544, 2023). "Ultimately, there would be therapeutic inefficacy of the ACE inhibitor, resulting in the ineffective treatment of hypertension." (PMID 36771707, 2023). "The inhibitory activities of the herbal extracts were assessed on the key enzymes that control the occurrence of some NCDs including type II diabetes (T2DM) (α-amylase and α-glucosidase), Alzheimer’s disease (AChE, BChE, and BACE-1) and hypertension (ACE)." (PMID 38066118, 2023). "SFH, derived from alcalase hydrolysis with a hydrolysis degree of 17%, inhibits ACE, strictly correlated with the development of hypertension and atherosclerosis." (PMID 37960264, 2023). "Angiotensin-converting enzyme (ACE) inhibitors and angiotensin receptor blockers are both classes of drugs used in the management of hypertension, heart failure, chronic kidney disease, and proteinuria." (PMID 37213987, 2023). "Thiazide or thiazide-like diuretics also had a better safety profile compared to ACE inhibitors which, according to that study, makes them an attractive option for first-line treatment of hypertension." (PMID 36991144, 2023). "The synthetic ACE inhibitors, including captopril, enalapril, ramipril, and benazepril, are extensively used for the treatment of essential hypertension in humans." (PMID 37446242, 2023). "In prior research, we found that the DD genotype of the ACE gene was related to essential hypertension in the Ethiopian population." (PMID 37200278, 2023). "In reflection of high mortality and morbidity, ACE inhibitors were superior to ARBs in patients with high blood pressure and type 2 diabetes mellitus." (PMID 37299008, 2023). "It has also been observed that patients with essential hypertension are treated with ACE inhibitors because of their effect on vascular remodeling responses." (PMID 37733712, 2023). "The angiotensin-I-converting enzyme (ACE) inhibitor is one of several classes of anti-hypertensive medicine available to reduce the elevated systolic blood pressure (SBP) in high blood pressure patients." (PMID 37299008, 2023). "Although ARBs have a good safety profile, ACE inhibitors have additional benefits when it comes to the management of diabetic patients with high blood pressure." (PMID 37299008, 2023). "Clinically, the inhibition of ACE activity to suppress the formation of Ang II has been considered an efficient strategy for the management of high blood pressure." (PMID 37446561, 2023). "The anti-hypertensive effect of some cheese varieties occurs through the action of three peptides on the inhibition of ACE, thus producing a beneficial impact in individuals with high blood pressure." (PMID 38231707, 2023). "There was controversy surrounding the continued use of ACE inhibitors (ACEIs) and angiotensin-receptor blockers (ARBs) to treat hypertension early in the pandemic." (PMID 35991665, 2022). "CA modulates the renin-angiotensin-aldosterone endocrine axis in vitro, and in cyclosporine-induced hypertension experiments in Sprague-Dawley rats, CA significantly reduced plasma angiotensin-converting enzyme (ACE) activity." (PMID 35669732, 2022).
Hypertension (continued). "In the treatment of hypertension, angiotensin-converting enzyme (ACE) inhibitors, Ang II type 1 receptor (AT1R) antagonists, and mineralocorticoid receptor antagonists are cornerstones in blocking RAS." (PMID 36312232, 2022). "The potent ACE-inhibitory peptides from natural casein hydrolysate have been widely studied as a safe alternative to synthetic ACE inhibitors for hypertension treatment." (PMID 36235859, 2022). "PA, as an angiotensin converting enzyme (ACE) inhibitor, is widely used in cardiovascular diseases, especially in systemic hypertension and heart failure." (PMID 35408631, 2022). "For example, captopril is an angiotensin-converting enzyme (ACE) inhibitor that is primarily used to treat hypertension and congestive heart failure." (PMID 35148844, 2022). "In the case of abnormal metabolism, ACE would catalyze degradation and inactivation of bradykinin, a vasodilator, which lead to trigger excessive levels of angiotensin II and lead to hypertension." (PMID 35923206, 2022). "The main reason of this poor agreement is that in vitro tests reflect only the interaction of the inhibitors (e.g., peptides) with ACE, and in vivo tests account for many other possible physiological factors involved in the manifestation of hypertension." (PMID 36558516, 2022). "The buildup of ROS causes overexpression of the angiotensin-converting enzyme (ACE), which is a significant risk factor for cardiovascular disease (CVD) and hypertension." (PMID 35204069, 2022). "We explored renal cell cancer (RCC) survival among users of antihypertensive medication as hypertension is proposed to be a risk factor for RCC and ACE-inhibitors and angiotensin receptor blockers (ARBs) have been associated with improved prognosis of RCC." (PMID 34921656, 2022). "When disaggregating by treatment required, 410 (20.0%) people required treatment for hypertension; 69 (3.3%) for diabetes; 74 (3.2%) for statin and/or aspirin; and 18 (0.6%) required an ACE-inhibitor." (PMID 36084117, 2022). "In this section, we reviewed studies that discussed the effects of ACE inhibitors and ARBs on the patients with hypertension in the context of the COVID-19 pandemic." (PMID 35075396, 2022). "Data on direct effects on hypertension are also available in the literature and focus on the inhibition of the angiotensin-converting enzyme (ACE), renin-angiotensin system, and blood pressure in vitro and in biological systems." (PMID 36557936, 2022). "For the treatment of hypertension in diabetes, calcium channel blockers or angiotensin-converting enzyme (ACE) inhibitors are frequently prescribed as a single drug or in combination." (PMID 36085061, 2022). "Multiple epidemiologic studies have revealed that serum ACE levels are abnormally increased in patients with cardiovascular disease and hypertension and are connected to coronary artery stenosis." (PMID 36110446, 2022). "The ACE inhibitor hypertension drug relieves vasoconstriction by inhibiting ACE expression and increasing ACE2 expression, which restricts the conversion of angiotensin I to angiotensin II." (PMID 36293371, 2022). "Presently, angiotensin-converting enzyme (ACE) inhibitors and angiotensin II receptor blockers (ARBs) are used worldwide to treat hypertension; the antihypertensive effects of ACE inhibitors and ARBs are led by the inhibition of angiotensin II production." (PMID 35214118, 2022). "Ang I is a vasopressor substance and BK acts as a hypotensive oligopeptide, ACE inhibition is deemed to be an effective way for hypertension prevention and treatment." (PMID 36082025, 2022). "Since the renoprotective effects of angiotensin-converting enzyme (ACE) inhibitors before overt hypertension in AS were shown, renin–angiotensin system (RAS) inhibitor treatment should be initiated even if the patient was not hypertensive." (PMID 36292665, 2022).
Hypertension (continued). "The link between food peptides, gut microbiota, and hypertension is then mainly due to the inhibition of ACE, which will slow the conversion of angiotensin I to angiotensin II, resulting in vasoconstriction suppression and blood pressure lowering." (PMID 36557936, 2022). "We assessed the association of ACE and ACE2 polymorphisms with disease severity using logistic regression analysis adjusted by age, sex, hypertension, type 2 diabetes, and obesity." (PMID 35250987, 2022). "Eleven of 18 patients had controlled hypertension with two or three antihypertensive medicaments (6 from group I and 5 from group II; 2 from each group received ACE inhibitors)." (PMID 35039571, 2022). "Bioactive peptides derived from various dairy sources have shown efficacy in reducing hypertension by inhibiting ACE in both in vitro and in vivo studies." (PMID 36010429, 2022). "The in vitro ACE-inhibitory capability of brewing protein hydrolysates makes them promising natural compounds to manage hypertension." (PMID 36294989, 2022). "In summary, although ACE inhibitors have numerous indications and are the cornerstone of hypertension, chronic kidney disease and heart failure management, this study finds evidence for a beneficial effect of cerebral cortex ACE in preventing AD." (PMID 36046424, 2022). "The present finding also showed that individuals with the DD genotype of the ACE gene are about three times more likely to have hypertension than those with II genotype [OR = 3.38: 95% CI (1.44, 7.96)]." (PMID 36355860, 2022). "Previous studies have reported that among patients with COVID-19 and coexisting hypertension, mortality was lower when ACE inhibitors or angiotensin II receptor blockers (ARBs) were administered than when they were not provided." (PMID 36015068, 2022). "ACE-1 inhibitory peptides are effectively used to maintain normal blood pressure and prevent hypertension and are found as the bioactive components of protein hydrolysates or concentrates sold for prevention of high blood pressure." (PMID 36551234, 2022). "Angiotensin converting enzyme (ACE) inhibitors are commonly used for treatment of hypertension and heart failure with reduced ejection fraction (HFrEF)." (PMID 35906533, 2022). "In this study, we screen the potential targets of BAC in the CVDPlatform and found that ACE/ACE2 are the potential targets for anti-hypertension." (PMID 35359841, 2022). "The somatic isoform of angiotensin I‐converting enzyme (sACE) plays a critical role in blood pressure regulation, and ACE inhibitors are thus widely used to treat hypertension and cardiovascular disease." (PMID 35818993, 2022). "Most (49%) people with new-onset hypertension were initially prescribed a single antihypertensive agent; most commonly angiotensin-converting enzyme (ACE) inhibitors or angiotensin receptor blockers (ARBs) (47.8%, N = 106)." (PMID 35201530, 2022). "According to the WHO, three types of drugs are successful for treatment of hypertension: Thiazide and Thiazide-like agents, Angiotensin-1-converting enzyme (ACE-1; EC 3.4.15.1) inhibitors and long-acting Dihydropyridine calcium channel blockers." (PMID 36551234, 2022). "The importance of the RAS in the developmental programming of hypertension has been shown by the ACE inhibitor to normalize blood pressure in undernourished offspring, relative to their control counterparts." (PMID 35955421, 2022). "ACE is known to convert Ang I to Ang II, which contributes to VSMCs proliferation and vascular remodeling in hypertension." (PMID 35832088, 2022). "Angiotensin converting enzyme (ACE) inhibitors or angiotensin receptor blockers (ARBs) are used as first-line drugs for the management of hypertension." (PMID 36230773, 2022). "Ramipril is an ACE-i (angiotensin-converting enzyme inhibitor) that is used for several indications such as hypertension or the prevention of heart failure progression." (PMID 35448480, 2022).
Hypertension (continued). "If present, both hypertension and proteinuria can be addressed with the use of renoprotective ACE inhibitors, which decrease arterial blood pressure by RAAS inhibition and reduce proteinuria by a reduction in intraglomerular pressure." (PMID 36009441, 2022). "Drug treatment for hypertension included angiotensin converting enzyme (ACE) inhibitors or angiotensin II type 1 receptor antagonists, whereas all dyslipidemic patients were on statins." (PMID 35883722, 2022). "In this sense, ACE inhibitors are bioactive substances that are potentially used as drugs to treat or prevent hypertension, heart failure, myocardial infarction, and other important diseases." (PMID 36143487, 2022). "Patients experiencing aggravated hypertension were predominantly dispensed ACE inhibitors, ARBs, and CCBs at baseline and their use of diuretics increased after aggravation." (PMID 35201530, 2022). "The insertion/deletion (I/D) (rs4646994) polymorphism in intron 16 of the ACE gene is considered an important genetic determinant of CAD and hypertension." (PMID 35741131, 2022). "The current standard care for the treatment of hypertension includes drugs which are mostly synthetic ACE-inhibitors, such as captopril and enalapril, to name a few." (PMID 35479750, 2022). "This study isolated and identified a new ACE inhibitor derived from LMPH that is promising as a natural alternative to synthetic hypertension drugs." (PMID 35804705, 2022). "One of the most important therapeutic modalities for the management of hypertension is the inhibition of the angiotensin-converting enzyme (ACE)." (PMID 36143487, 2022). "Anthocyanins have antihypertensive effects by inhibiting ACE activity and have also been shown to prevent hypertension." (PMID 36117602, 2022). "Most patients receive ACE inhibitors for treatment of hypertension, HFrEF, or coronary artery disease." (PMID 35906533, 2022). "Perindopril arginine (PA) as an angiotensin-converting enzyme (ACE) inhibitor is widely used in cardiovascular diseases, especially in systemic hypertension and heart failure." (PMID 35408631, 2022). "Of note, one obese patient out of twelve was taking cholesterol-lowering drugs and skeletal muscle relaxants and two were receiving angiotensin-converting enzyme (ACE) inhibitors to treat hypertension." (PMID 35955459, 2022). "More importantly, however, our data support a more prominent role of the intratubular renin/ACE/Ang II/AT1a/NHE3 axis in the proximal tubules in the development of 2K1C hypertension." (PMID 36555438, 2022). "The observation is consistent with the previous studies that a major hypertension target, angiotensin-converting enzyme (ACE) is also involved in AD." (PMID 36437990, 2022). "The generation of renin results in the increased production of angiotensin I and ACE-1 is responsible for the conversion of angiotensin I to the potent vasoconstrictor angiotensin II, which results in elevated blood pressure and hypertension activity." (PMID 35206049, 2022). "There are many ACE inhibitors on the market, such as captopril, ramipril, and enalapril, which are widely applied in the clinical treatment of hypertension." (PMID 36080189, 2022). "This work reveals for the first time that low-molecular-weight peptides from H. nipponia have ACE inhibitory activity, which can provide a new explanation for leech treatment of hypertension." (PMID 36080189, 2022). "ACE inhibition is a well-established technique for developing pharmaceuticals for the treatment of hypertension." (PMID 35571042, 2022). "BMI, the presence of diabetes, hypertension, or cardiovascular disease, the use of ACE inhibitors/ARBs, and COVID-19 severity at the time of admission were not well balanced between the fully and not fully vaccinated groups." (PMID 36362579, 2022). "Grade 2 (BP more than 140/90 mmHg) and more hypertension should be managed with the addition of antihypertensive drugs, starting with angiotensin-converting enzyme (ACE) inhibitors." (PMID 36199644, 2022).
Hypertension (continued). "The decrease of ACE2 from the cell surface by endocytosis and enzymatic degradation results in ACE/ACE2 imbalance and dominance of the ACE-mediated pathway leading to hypertension, acute lung injury, and multiorgan damage." (PMID 35769458, 2022). "Shellfish polysaccharides can inhibit ACE and prevent the conversion of Ang I to Ang II, which is an effective method to reduce hypertension." (PMID 36176638, 2022). "It has been reported that shellfish polysaccharides are potent ACE inhibitors and can regulate NO levels; thus, these compounds have the potential to be developed as functional foods to prevent hypertension." (PMID 36176638, 2022). "The medication was developed specifically for use in patients with renal impairment to treat hypertension through manipulation of metabolism and excretion, which distinguishes it from other members of the ACE inhibitor drug class." (PMID 36386190, 2022). "The persistent sympathetic over-activity in hypertension promotes the NE release to adventitia of artery, and thus increases EVs release from AFs and the ACE contents in the EVs." (PMID 35832088, 2022). "Patients with TSC2-polycystic kidney disease 1 deletion syndrome and hypertension treated with ACE inhibitors or angiotensin receptor blockers had decreased renal AML development compared to control." (PMID 36220392, 2022). "A large body of studies are devoted to demonstrate the therapeutic potential of ACE inhibitors for hypertension." (PMID 35530510, 2022). "Hypertension is regulated by various mechanisms, one of which is related to the activity of the angiotensin-converting enzyme (ACE)." (PMID 36185652, 2022). "Hypertension studies have confirmed that ACE inhibitors potentiate the antihypertensive effects of diuretics, but the interaction appears to be additive rather than synergistic." (PMID 36143487, 2022). "In hypertension, ACE is upregulated and active in converting its main substrate, angiotensin I (Ang I), to angiotensin II (Ang II)." (PMID 36016727, 2022). "In summary, AGT suppression lowers BP to the same degree as classical RAS blockers like ACE inhibitors and ARBs in a variety of hypertension models, and this effect is largely due to interference with tissue angiotensin generation." (PMID 35904033, 2022). "The beneficial effects of ACE-inhibitory peptides on hypertension are not limited to ACE inhibition, but also can improve vascular function disorder." (PMID 35479750, 2022). "Although many HD patients receive ACE inhibitors/ARBs for hypertension control, they hold the drugs on dialysis days to prevent intradialytic hypotension and inadequate dialysis." (PMID 36084024, 2022). "As it is known, ACE converts angiotensin I to angiotensin II, which is a potent vasoconstrictor peptide primarily involved in the pathogenesis of hypertension and exerts its effect via angiotensin II type 1 receptors." (PMID 35585878, 2022). "A variety of synthetic ACE inhibitors, including captopril, enalapril, and lisinopril fosinopril have been extensively employed in attempted hypertension treatments." (PMID 36499176, 2022). "Due to the use of ACE inhibitors in the treatment of hypertension and heart failure, there is considerable interest in understanding the function and expression of ACE2 in various human organs." (PMID 36148474, 2022). "Ramipril is an ACE inhibitor used for the management of hypertension and the reduction of cardiovascular mortality following myocardial infarction in hemodynamically stable patients with clinical signs of congestive heart failure." (PMID 35443763, 2022). "Following these events, angiotensin I is converted into angiotensin II by the action of angiotensin-I-converting enzyme, which results in the generation of increased blood pressure and hypertension." (PMID 35206049, 2022). "The centrality of ACE in the RAAS led to the early development of ACE inhibitors for the treatment of hypertension." (PMID 35818993, 2022).